TYRO3 (TYRO3 protein tyrosine kinase)
Diseases named in the same sentence as TYRO3 in open-access papers (continued):
Sharing a sentence is not in itself a finding about the gene and the disease.
cancer (continued). "UNC3810A, a small molecule inhibitor of the receptor tyrosine kinase Tyro3, a member of the Tyro3/Axl/Mer (TAM) family of tyrosine kinases that promote the proliferation and survival of several cancers, was shown to be a potent inhibitor of PEL cell growth in a mouse xenograft model." (PMID 34578378, 2021). "The expression of MER, TYRO3, and AXL were profiled among multiple human cancer cells." (PMID 32042425, 2020). "A recent report found that AXL, but not the other two members of the same family MERTK or TYRO3, is cleaved by α- and γ-secretases in cancer cell lines to generate an AXL intracellular isoform." (PMID 32992696, 2020). "This review will focus on PtdSer as a cofactor required for stimulating TYRO3, AXL and MERTK – comprising the TAM family of receptor tyrosine kinases by their ligands Protein S (PROS1) and growth-arrest-specific 6 (GAS6) in inflammation and cancer." (PMID 31775787, 2019). "TYRO3 depletion significantly decreased the number of viable MGH-U3 and RT112 colonies in soft agar assays, by 80 and 60% respectively, demonstrating a role for TYRO3 in regulating the survival of clonogenic cancer cells." (PMID 30765874, 2019). "Importantly, transcriptomics analysis of the screened 941 cancer cell lines revealed that high AXL and TYRO3 mRNA levels predict both resistance to necroptosis and low RIPK3 mRNA levels, but not those of RIPK1, MLKL, or any other pro-necroptotic genes." (PMID 30157175, 2018). "In many cases, the normal physiologic functions for a given oncogenic protein are co-opted by cancer cells to promote tumorigenesis and TYRO3 is not an exception." (PMID 30501104, 2018). "In the present study, we systematically characterized the proteolytic process of TAM receptors and found that AXL, but not MERTK or TYRO3, is efficiently and sequentially processed by α- and γ-secretases in 7 types of cancer cells." (PMID 28034848, 2017). "We found that AXL-FL, but not MERTK or TYRO3, was very efficiently cleaved by α- and γ-secretases in various types of cancer cell lines." (PMID 28034848, 2017). "Three more SNPs (Gga_rs14524377, Gga_rs13878108 and GGaluGA217414) having association with IMFBr were in the proximity of protein tyrosine kinase (TYRO3), microsomal glutathione S-transferase 1 (MGST1) and nucleoside-triphosphatase, cancer-related (NTPCR) genes, on GGA5, GGA1 and GGA3, respectively." (PMID 23834466, 2013). "Additionally, TYRO3 could inhibit the EMT process by down-regulating ENO1, which may be achieved by interfering with energy metabolism in cancer cells." (PMID 37116196, 2023). "Further synthesis and in vitro tests of this compound against various cancer cell lines, where Axl, ABL1, and Tyro3 play a significant role in proliferation, division and metastases are further steps to be taken, and further indications for TAM inhibition may follow." (PMID 32117858, 2019). "In addition, ProS1 protected cancer cells from acute apoptosis induced by staurosporine, as well as additionally, long-term serum starvation-induced apoptosis in MGH-U3 cells (Tyro3 only), which reflects its additional coupling to Akt signalling in these cells." (PMID 31766614, 2019). "A 4-day treatment of A375 and SkMel28 cancer cell lines, which have no initial RIPK3 expression (but also no genetic mutations of RIPK3), with low concentrations of AXL/TYRO3 inhibitor BMS-777607 resulted in a regain of RIPK3 expression at both mRNA and protein levels." (PMID 30157175, 2018). "Furthermore, in cells where Tyro3 is the sole TAM receptor and therefore gateway for all TAM ligands, we have shown that it is connected to both Erk and Akt signalling pathways and hence able to potentially regulate both cancer cell proliferation and survival respectively." (PMID 31766614, 2019). "Consistent with the in vitro data, nuclear localisation of AXL and TYRO3 receptors was reported in cancer tissues, including schwannoma, radioresistant triple-negative breast cancer (AXL), CRC, and leiomyosarcoma (TYRO3)." (PMID 40044635, 2025).
cancer (continued). "We profiled the expression of MER among multiple human cancer cells and found that MER and TYRO3, but not AXL, show high levels of protein expression in G361 cells." (PMID 32042425, 2020). "In the present study, we demonstrate that AXL, but not TYRO3 or MERTK, is efficiently and sequentially cleaved by α- and γ-secretases in various types of cancer cell lines." (PMID 28034848, 2017). "Moreover, TAM (TYRO3, AXL, and MERTK) family also had negative influence on cancer immunotherapy by mediating efferocytosis, negative regulating of dendritic cell activity, and dysregulating production of chemokines." (PMID 36341335, 2022).
infection (14 papers, 2013 to 2025). The state of being infected such as from the introduction of a foreign agent such as serum, vaccine, antigenic substance or organism. "Alongside the increased ZIKV loads in the SH-SY5Y cells, IFN-beta transcript levels and receptors Tyro3/MER-TK were upregulated at early timepoints of infection." (PMID 41373653, 2025). "When HER2 expression was reduced by two different siRNAs, the phosphorylation levels of TYRO3 after infection were reduced by nearly 40% and 70%, respectively, compared to the control siRNA-treated cells." (PMID 33052961, 2020). "However, the expression of Tyro-3 was reduced upon infection compared with the mock-infected cells (set at 1) (0.63 ± 0.16, p = 0.025)." (PMID 36989308, 2023). "Many reports have shown that the AXL and TYRO3 of the TAM receptors could potentiate the infection of various viruses in different pathways." (PMID 32172658, 2020). "In Huh 7.0 cells, a TYRO3- and MERTK-positive cell line, EBOVΔVP30 infection induced the phosphorylation of TYRO3 in a HER2-dependent manner, but infection did not induce phosphorylation of MERTK." (PMID 33052961, 2020). "For example, ectopic expression of TYRO3 and AXL enhances infection of all DENV serotypes, as well as other related viruses such as WNV and YFV." (PMID 32172658, 2020). "Both Tyro-3 and MER-TK gene expression was significantly (p < 0.05) upregulated at 2 h (the early tested timepoint), but at the later tested timepoint of 48 h, we noted significant (p < 0.05) downregulation of these two receptors upon ZIKV post infection." (PMID 41373653, 2025). "Overall, at the maternal/fetal interface, different cell types express cell-surface factors that allow viral entry and infection, replication and further transmission to the fetus, such as Axl, Tyro3 and TIM1 that belong to the ZIKV PS receptors of the TAM (i.e., Tyro3 and Axl) and TIM families." (PMID 33810028, 2021). "We also found a 70% reduction in infection of cells treated with one TYRO3 shRNA which reduced gene expression by 62% but did not reduce protein expression (data not shown)." (PMID 23573288, 2013). "LCMV-WE infection also induced expression of a non-conventional virus receptor, AXL-1, from the TAM (TYRO3/AXL/MERTK) family of receptor tyrosine kinases and this expression correlated with proliferation." (PMID 25822203, 2015). "While PHx, similar to LCMV infection, slightly up-regulated expression of Tyro-3 and LSECtin in liver, PHx did not affect expression of Axl-1 mRNA, which was almost 6-fold higher in LCMV-WE-infected livers at day 8 after infection." (PMID 25822203, 2015).
kidney disease (3 papers, 2020 to 2023). "Whereas CTSH and DLK1 have not been associated with kidney disease, studies have shown increased TYRO3 mRNA expression and increased circulating and urinary TYRO3 levels in patients with DKD, further supporting a causal role." (PMID 36349687, 2023). "Recently, Mer and Tyro3 have been reported to suppress kidney dysfunction, which means the blockade of AXL and induction of Mer and Tyro3 signaling might be a promising way to cure the kidney diseases in future." (PMID 32324796, 2020).
Cardiovascular Disease (2 papers, 2019 to 2024). "Further studies are needed to elucidate the function of Tyro3 in cardiovascular disease." (PMID 39684449, 2024). "Of the TAM receptors, Tyro3 remains the least studied in cardiovascular disease, and the few studies that exist suggest that Tyro3 could be a therapeutic target after myocardial injury." (PMID 39684449, 2024). "Although representing a broad range of physiological activities, the functions of Tyro3, Axl, and Mer receptors may be critically important to target in the development of novel therapeutics for the treatment of cardiovascular disease." (PMID 39684449, 2024). "Tyro3 remains to be the least studied of the TAM receptors, particularly in the area of cardiovascular disease." (PMID 30980657, 2019). "Because of the low levels of expression of Tyro3 in the vasculature compared with the central nervous system and the reproductive system, the function of Tyro3 in cardiovascular disease has not been studied in detail." (PMID 39684449, 2024).
colorectal (2 papers, 2020 to 2024). "EGCG reversed cisplatin resistance by downregulating AXL and TYRO3 expression in NSCLC and sensitizing 5-FU-resistant colorectal cancer." (PMID 32051483, 2020).
hematologic malignancies (1 paper, 2016). "Further investigation into the role of TYRO3 in hematologic malignancies is warranted." (PMID 27834816, 2016). "Targeted inhibition of members of the TAM (TYRO-3, AXL, MERTK) family of receptor tyrosine kinases has recently been investigated as a novel strategy for treatment of hematologic malignancies." (PMID 27834816, 2016). "In summary, targeted inhibition of members of the TAM (TYRO-3, AXL, MERTK) family of receptor tyrosine kinases has recently been investigated as a novel strategy for treatment of hematologic malignancies." (PMID 27834816, 2016).
intestinal diseases (1 paper, 2023). "Several of these genes, including Ralbp1, Pfas, Tyro3, Opcml, Syne2, Six4, Tll2, and Slc23a2, were previously implicated in gut microbiome abundance, metabolic traits, and several intestinal diseases." (PMID 37420306, 2023).
neurodegenerative disease (1 paper, 2018). A disorder of the central nervous system characterized by gradual and progressive loss of neural tissue and neurologic function. "Tyro3-/-Axl-/-Mertk-/- triple-KO mice exhibit loss of neurons in old age73, but no phenotype of Tyro3 overactivation has been reported, and it is not possible to confidently speculate whether this protein promotes FTLD or other neurodegenerative diseases." (PMID 29382817, 2018).
TYRO3 also shares sentences with these, for which no sentence is quoted: acute lymphoblastic leukemia (2 papers); Anorexia (2); lymphoproliferative disorder (2); metastatic melanoma (2); non-small cell lung carcinoma (2); acral melanoma (1); acute leukemia (1); adenocarcinoma (1); autoimmune hepatitis (1); cervical carcinoma (1); chronic myelogenous leukemia (1); chronic periodontitis (1); Cognitive impairment (1); cutaneous melanoma (1); diffuse intrinsic pontine glioma (1); gastric adenocarcinoma (1); gastrointestinal disorders (1); gingivitis (1); glioma (1); head and neck squamous cell carcinoma (1); hematoma (1); inflammatory bowel disease (1); kidney cancer (1); liposarcoma (1); liver cancer (1); Liver Disease (1); lung adenocarcinoma (1); multiple sclerosis (1); myoclonic epilepsy (1); neuroblastoma (1).
A further 11 diseases each share a sentence with TYRO3 in 1 paper.